GLI1 (GLI family zinc finger 1)
Diseases named in the same sentence as GLI1 in open-access papers (continued):
Sharing a sentence is not in itself a finding about the gene and the disease.
esophageal adenocarcinoma (18 papers, 2014 to 2025). A malignant tumor with glandular differentiation arising predominantly from Barrett mucosa in the lower third of the esophagus. "The GLI1 phosphorylation at p.Ser84 was observed upon TNF-α treatment and was suggested to increase GLI1 oncogenic function in the development of esophageal adenocarcinoma, since cells with the GLI1 mutation, p.Ser84Glu had a higher level of colony formation in a soft-agar assay." (PMID 33081032, 2020). "Atypical activation of GLI1 has been observed in esophageal adenocarcinoma (EAC) via the mTOR/S6K1 pathway which activates the transcription and oncogenic function of GLI1 phosphorylation by S6K1." (PMID 34944780, 2021). "SMO-independent activation of GLI1 has been detected in several malignant tumors such as esophageal adenocarcinoma whereby activated S6K1 phosphorylates GLI1 at Ser84 to induce GLI1 transcriptional activity and oncogenic functions." (PMID 33637972, 2021). "A similar conclusion was reached in a recent study on Barrett ́s esophagus cells, where omeprazole suppressed Hedgehog/Gli1 signaling and induced G0/G1 cell cycle arrest." (PMID 32164284, 2020). "Here, we show that esophageal adenocarcinoma (EAC) cell lines are insensitive to vismodegib (SMO inhibitor) but respond to GANT61 (GLI1 inhibitor)." (PMID 32913560, 2020). "The mammalian target of rapamicin (mTOR)/S6K1 pathway has been proposed to mediates the development of esophageal adenocarcinoma (EAC) through GLI1 activation in a SMO-independent manner." (PMID 30934935, 2019). "For instance, S6K1 and aPKCι/λ directly phosphorylate and activate GLI1, respectively, in esophageal adenocarcinoma and BCC cells." (PMID 30934935, 2019). "Recently, the mTOR/S6K1 pathway was shown to mediate the development of esophageal adenocarcinoma (EAC) through GLI1 signaling." (PMID 25134527, 2014). "However, studies on esophageal adenocarcinoma cells suggest that TNF-alpha activates GLI proteins through the mTOR pathway, specifically involving S6K1-mediated phosphorylation of GLI1 at Ser84." (PMID 39568072, 2024). "Notably, mTOR/S6K1-mediated phosphorylation appears to facilitate the release of GLI1 protein from its cytoplasmic repressor SUFU, thereby enhancing the overall oncogenicity of GLI1 in esophageal adenocarcinoma cells." (PMID 28122581, 2017). "Moreover, S6K1 kinase has been shown to phosphorylate GLI1, the effector of HH signaling, promoting GLI1 transcriptional activity and oncogenic function in esophageal adenocarcinoma." (PMID 25134527, 2014). "In esophageal adenocarcinoma (EAC), GLI-inhibitor (Gli-i) upregulated E-cadherin expression while downregulating N-cadherin and β-catenin expression by inhibiting GLI1 and GLI2 transcriptional activity." (PMID 31547193, 2019). "In esophageal adenocarcinoma, S6K1 was demonstrated to have the capacity to phosphorylate GLI1 increasing its transcriptional activity." (PMID 25134527, 2014). "The reduction in pS6 was accompanied by a decrease in Gli1 expression, consistent with previous reports of non-canonical Gli1 regulation through mTOR/S6 signaling, as observed in esophageal adenocarcinoma cells." (PMID 40565186, 2025). "We could recently show that GLI1 is activated via ERBB2 and PI3K/AKT/mTOR in esophageal adenocarcinoma in a SMO-independent manner." (PMID 28418873, 2017). "Both canonical and noncanonical activation of GLI1 was reported in esophageal adenocarcinoma." (PMID 36010600, 2022). "Another group could demonstrate a non-canonical activation of GLI1 in esophageal adenocarcinoma via TNF-α and subsequently mTOR/S6K1 while Zhou and colleagues could recently show that GLI1 and GLI2 are non-canonically activated via PI3K/AKT in human renal cell carcinoma." (PMID 28418873, 2017). "TNF-α selectively stimulates GLI1 and promotes GLI1 nuclear localization via mTOR phosphorylation of S6K1 in human esophageal adenocarcinoma cell lines, independent of SMO." (PMID 36010600, 2022).
liver fibrosis (18 papers, 2012 to 2026). "The findings of the present study support that Gli1 may serve as a potential therapeutic target to ameliorate liver fibrosis caused by various modes of chronic insults." (PMID 38646644, 2024). "Saikosaponin b1 attenuates liver fibrosis by competitively disrupting the interaction between signal transducer and activator of transcription 3 (STAT3) and glioma‐associated oncogene‐1 (Gli1) in the activated hepatic stellate cells (HSCs)." (PMID 41163803, 2025). "The findings underscore that HPC-originated DR occurred in various extent during different modes of hepatic injury, and facilitated the progression of liver fibrosis; and that Gli1 regulated HPC-originated DR, and subsequently accelerated hepatic fibrosis." (PMID 38646644, 2024). "It has been reported that canonical Hh/Gli1 signaling regulated HSC-mediated liver angiogenesis promoting liver fibrosis." (PMID 38646644, 2024). "Gant61 (a Gli1/2 transcription factor inhibitor), Gant61 alleviates liver fibrosis by decreasing the number of HSCs and decreasing the mRNA and protein levels of Smo, Gli1, Gli2." (PMID 38202710, 2023). "The SHH signaling is suggested to be mediated through its immediate target GLI2 in hepatic fibrosis since GLI1 expression was found rather sparse in HSCs." (PMID 24312641, 2013). "This study provides novel evidence that plant-derived miR-55—originating from the traditional Chinese formula Ge Xia Zhu Yu Decoction—can be orally delivered and modulates the CK2α/SMO/Gli1 signaling axis, significantly ameliorating MAFLD-associated liver fibrosis." (PMID 41596397, 2026). "Noteworthy, in liver fibrosis, Gli1 has been clarified as a promoter for HIF-1α." (PMID 36811777, 2023). "Peribiliary Gli1+ mesenchymal cells are a subset of stromal cells characterized by active hedgehog signaling; these cells proliferate, acquire a myofibroblast phenotype, and surround the biliary tree in response to cholestatic injury, promoting liver fibrosis." (PMID 34805276, 2021). "The “protein regulator of cytokinesis 1” (PRC1), which regulates the Wnt/β-catenin signaling pathway, may induce Gli1-dependent osteopontin expression to contribute to liver fibrosis." (PMID 34805276, 2021). "Thus, in our results we observed Gli1+ cells proliferate and differentiate into myofibroblasts in liver fibrosis." (PMID 31695785, 2019). "In mice receiving 3‐weeks CCl4 injection, knockdown of STAT3 inhibited the expression of both fibrotic biomarkers and Gli1 compared with the un‐knockdown group, suggesting that STAT3 was important for CCl4‐induced liver fibrosis." (PMID 41163803, 2025). "In the same context, the current results reveal the correlation between the hepatic fibrosis prompted by DEN and the marked stimulation of Hh signaling, as clarified by the amplified gene expressions of Ptch1 as well as Gli1 and Gli2." (PMID 36811777, 2023). "And it inhibited the activation of HSCs by regulating TGFβ1/NDRG2/MAPK signaling axis in CCl4-induced liver fibrosis Our study newly found that NLPC0393 inhibited the differentiation of WB-F344 cells into cholangiocytes in a Gli1-dependent manner." (PMID 36483737, 2022). "In the CCl4‐induced liver fibrosis model in mice, IHC staining showed that in the vehicle group there was minimal expression of SMO and GLI1 in normal liver tissues, but increased expression in the CCl4 group." (PMID 31328391, 2019). "Ssb1 prevented liver fibrogenesis in the TAA and CCl4‐induced animal models by suppressing STAT3 activation and blocking STAT3/Gli1 interaction, and specific knockdown of STAT3 in mice liver further strengthened the critical role of STAT3 in the Ssb1 treatment of liver fibrosis." (PMID 41163803, 2025). "Overall, the antifibrosis determination in animals showed that Ssb1 could reduce the indices of liver fibrosis in the TAA and CCl4‐induced models and regulate STAT3 phosphorylation and p‐STAT3/Gli1 interaction in fibrotic livers." (PMID 41163803, 2025).
liver fibrosis (continued). "Given the importance of Hh signaling in mediating T cell development and cytotoxic functions, and its enrichment as leading GSEA hit, we confirmed differential RNA expression in CD8 T cells in disparate liver fibrosis severities in HCV infection by qPCR analysis of PTCH1, SMO, and GLI1 mRNA." (PMID 38887299, 2024). "Then, GLI1/GLI2 was silenced and overexpressed in mouse intrahepatic bile duct epithelial cells (mIBECs) and BA animals to investigate changes in the mRNA and protein expression of EMT key factors and liver fibrosis indicators." (PMID 35692978, 2022). "After silencing and overexpression of GLI1/GLI2, immunofluorescence was used to detect the expression of cytokeratin-19 (CK19) and α-smooth muscle actin (α-SMA) in mIBECs, and hematoxylin and eosin (HE) staining and Masson staining were used to observe the degree of liver fibrosis in the BA animals." (PMID 35692978, 2022).
pancreatic ductal adenocarcinoma (18 papers, 2014 to 2025). An infiltrating adenocarcinoma that arises from the epithelial cells of the pancreas. "Lithium decreases the expression and activity of glioma-associated oncogene-1 (GLI1) blocking cell proliferation and G1/S cell cycle progression, triggering apoptosis and reducing the tumorigenicity of pancreatic ductal adenocarcinoma cells." (PMID 36836894, 2023). "Aberrant activation of the transcription factor GLI1, a central effector of the Hedgehog (HH) pathway, is associated with several malignancies, including pancreatic ductal adenocarcinoma (PDAC), one of most deadly human cancers." (PMID 25352983, 2014). "In a pancreatic ductal adenocarcinoma cell line, Gli1 was proved as a transcriptional factor of E-cadherin." (PMID 40508185, 2025). "In a pancreatic ductal adenocarcinoma cell line, knocking down Gli1 leads to β-catenin’s translocation into the nuclei, and the adherens junction is destroyed." (PMID 40508185, 2025). "Hedgehog-Gli1 signaling induces development of two common neurological features seen in pancreatic ductal adenocarcinoma (PDAC): peripheral neural invasion (PNI) and peripheral neural remodeling (PNR)." (PMID 38041128, 2023). "A recent study showed that lithium, a GSK3 inhibitor, upregulated the expression of Itch to downregulate Gli1 protein levels In pancreatic ductal adenocarcinoma (PDA) cell lines; however, the mechanism by lithium promotes itch expression remains unexplored." (PMID 34948134, 2021). "Gli1 is an important positive regulator of epithelial differentiation and decreased levels of Gli1 are likely to contribute to the highly metastatic phenotype observed in pancreatic ductal adenocarcinoma." (PMID 25069516, 2014). "GLI1 is expressed in different human malignancies including pancreatic ductal adenocarcinoma (PDAC) (Eberlet al., 2012;Fiaschiet al., 2009;Goelet al., 2013;Hui & Angers, 2011;Millset al., 2013;Rajurkaret al., 2012;Thayeret al., 2003)." (PMID 25352983, 2014). "ADAR1 enhances the function of GLI1 through A-to-I editing that leads to a change from arginine to glycine at Position 701, which boosted GLI1 transcriptional activity and therefore pro-tumorigenic phenotypes in pancreatic ductal adenocarcinoma." (PMID 39126156, 2025). "Moreover, the oncogenic KRAS is able to increase GLI1 transcriptional activity and protein levels in pancreatic ductal adenocarcinoma." (PMID 36765685, 2023). "Similarly, IKBKE directly promotes nuclear localization and transcriptional activity of GLI1 in pancreatic ductal adenocarcinoma." (PMID 33637972, 2021). "Our study sheds light on the intricate interplay among GLI1, MST1, and miR-301a, which connects the Hedgehog (Hh) and HIPPO/YAP signaling pathways in pancreatic ductal adenocarcinoma (PDAC)." (PMID 39846248, 2025). "GLI1 has been reported to activate the expression of DEC2, the DEC1 homologs, through a GLI binding site in the promoter in pancreatic ductal adenocarcinoma." (PMID 40133270, 2025). "In pancreatic ductal adenocarcinoma, increased PRMT1 expression correlates with GLI1 expression and leads to SMO-independent GLI1 activation, thereby mediating its oncogenic functions." (PMID 34006904, 2021). "In pancreatic ductal adenocarcinoma, both SOX9 and GLI1 are important to maintain the malignant phenotype of cancer stem cells." (PMID 29659575, 2018). "GLI1 and GLI2 are over-expressed and thought to participate in the development and progression of various cancers, especially pancreatic ductal adenocarcinoma (PDAC)." (PMID 26318045, 2015). "One study showed that high mobility group box protein SOX9 is a transcriptional target of Gli1 in KRAS-driven pancreatic ductal adenocarcinoma (PDA) and acts in a positive feedback loop to stabilize Gli1 by binding and sequestrating β-TRCP away from Gli1, which is thought to promote PDA." (PMID 34948134, 2021).
lung fibrosis (17 papers, 2016 to 2024). "Moreover, another GLI1 (glioma-associated oncogene homolog 1) positive perivascular lung resident MSCs population has been shown to contribute to myofibroblast formation in the bleomycin pulmonary fibrosis mouse model." (PMID 34290610, 2021). "Subsequent results reveal that the possible crosstalk mechanism involving TGF-β1/GLI1/Wnt/β-catenin signaling drives pulmonary fibrosis progression." (PMID 39766192, 2024). "It has been reported that Hh pathway expansion in GLI1+ MSCs instigates the progression of bleomycin-treated pulmonary fibrosis by upregulating bone morphogenetic protein antagonism." (PMID 39766192, 2024). "Reactivation of the Hh pathway and upregulation of GLI1 expression have been observed in conditions with fibrocyte-induced tissue fibrosis, such as idiopathic pulmonary fibrosis, biliary fibrosis, renal fibrosis, and cardiac fibrosis." (PMID 35595725, 2022). "Targeting hedgehog signaling proteins (GLI1/2) with GANT61 reduces bleomycin-induced increases in soluble collagen content in a bleomycin-driven mouse model of lung fibrosis." (PMID 36230980, 2022). "Inhibiting Gli-1 transcriptional activity is correlated with decreased lung fibrosis and collagen production." (PMID 34445632, 2021). "Lung tissues from patients with idiopathic pulmonary fibrosis have increased expression of GLI1 and GLI2 when compared to normal lung tissues." (PMID 35008794, 2021). "In this study, PQ inhibited the PI3K/Akt/mTOR autophagy signalling pathway, enhanced Hh signalling by increasing ROS, upregulated Smo and Gli1 protein levels, promoted pro-Fibrin protein expression, and exacerbated PQ-induced lung fibrosis." (PMID 30744607, 2019). "Recently, crosstalk between Wnt and Hh was shown to be involved in pulmonary fibrosis, and GLI1 was proved to be a potential therapeutic target in pulmonary fibrosis." (PMID 31867100, 2019). "Inhibition of Gli1 suppressed myofibroblast differentiation of LR-MSCs and pulmonary fibrosis, and decreased the expression of Wnt7b, Wnt10a and β-catenin." (PMID 29844390, 2018). "In our research, we found that Gli1 was increased much more significantly than the expression of Gli2 in the development of pulmonary fibrosis." (PMID 29844390, 2018). "We reported extremely increased expression of Wnt7b/10a, Fzd9/10 and Gli1 in the differentiation of LR-MSCs and lung fibrosis." (PMID 29844390, 2018). "In pulmonary fibrosis, GLI1 is upregulated in fibroblasts and myofibroblasts." (PMID 38967367, 2024). "However, the PI3K/Akt/mTOR autophagy signalling pathway was blocked by ligustrazin, which increased autophagy, decreased Hh signalling, downregulated Smo and Gli1 protein levels, suppressed pro-Fibrin expression, and ameliorated PQ-induced lung fibrosis." (PMID 30744607, 2019). "Thus, our study identified Wnt/β-catenin signaling and hedgehog signaling crosstalk in pulmonary fibrosis in vitro and in vivo, and highlighted Gli1 and Fzd10 as a potential therapeutic target in pulmonary fibrosis." (PMID 29844390, 2018). "In addition, the results showed that Gli1 was dramatically expressed and translocates to nucleus in myofibroblast-differentiated LR-MSCs and lung tissues derived from pulmonary fibrosis mouse models." (PMID 29844390, 2018). "In addition, blocking hedgehog pathway signaling through SHH or PTCH1 or directly knocking down GLI-1 and GlLI-2 proteins apparently lowered the level of bleomycin-induced pulmonary fibrosis in mice." (PMID 27486656, 2016). "In contrast, it was recently demonstrated that mice deficient in Gli1 were not protected from lung fibrosis suggesting either Gli2 or non-canonical hedgehog signaling may be regulating pathological effects in lung fibrosis." (PMID 32218238, 2020). "In addition, blocking hedgehog signaling by Gli1 inhibitor could also impair pulmonary fibrosis through defecting the transcription of Wnt7b/10a which were the target genes of Gli1." (PMID 29844390, 2018).
lung fibrosis (continued). "During PQ-induced pulmonary fibrosis, Smo, SHH, and Gli1 levels increased in lung tissues." (PMID 30744607, 2019). "Moreover, a study involving the use of a mouse model reported that treatment with GLI-1 siRNA and GLI-2 siRNA markedly inhibited the progression and severity of interstitial pulmonary fibrosis." (PMID 27486656, 2016). "Recent studies have shown that GLI-1 and GLI-2 play a major role in pulmonary fibrosis." (PMID 27486656, 2016). "Therefore, GLI-1 and GLI-2 play a critical role in interstitial pulmonary fibrosis." (PMID 27486656, 2016).